RN7SL456P (RNA, 7SL, cytoplasmic 456, pseudogene)
Gene: Miscellaneous RNA gene on chromosome 7 (147,940,007 to 147,940,301, forward strand). Ensembl gene ENSG00000242266.
Homologues: Orthologues: chimpanzee Metazoa_SRP (97% identical), macaque Metazoa_SRP (90% identical). Paralogues in human: RN7SL1 (80% identical), RN7SL2 (79% identical), RN7SL3 (79% identical), RN7SL664P (78% identical), RN7SL493P (78% identical), RN7SL126P (77% identical), RN7SL709P (77% identical), RN7SL383P (76% identical), RN7SL597P (76% identical), RN7SL630P (76% identical), RN7SL660P (76% identical), RN7SL125P (76% identical), and 701 more.